AGTR1 (angiotensin II receptor type 1)
Diseases named in the same sentence as AGTR1 in open-access papers (continued):
Sharing a sentence is not in itself a finding about the gene and the disease.
dyslipidaemia (2 papers, 2008 to 2024). "The AGTR1 rs5182 variant is related to nonalcoholic fatty liver disease, which is often characterized by dyslipidaemia." (PMID 39080710, 2024). "However, a study conducted in another Chinese population failed to observe a significant association between AGTR1 rs5182 and dyslipidaemia." (PMID 39080710, 2024). "Therefore, the combined effect of ACE I/D and AGTR1 rs5182 on lipid levels in the current study provides valuable insights into the intricate relationships between the RAS and dyslipidaemia." (PMID 39080710, 2024).
head and neck cancer (2 papers, 2018 to 2022). A primary or metastatic malignant neoplasm affecting the head and neck. "Because comparable data is not available for head and neck cancers, further inquiries into AGTR1 expression changes and underlying genetic alterations may help establish this gene and its signalling pathway as a legitimate therapeutic target." (PMID 29371888, 2018).
intrahepatic cholangiocarcinoma (2 papers, 2023 to 2026). A carcinoma that arises from the intrahepatic bile duct epithelium in any site of the intrahepatic biliary tree. "HIPPO/YAP1 signalling is also implicated in Ang II-mediated proliferation in intrahepatic cholangiocarcinoma (iCCA), with ARBs disrupting AGTR1+ cancer-associated fibroblast (CAF) MFAP5/Notch1 signalling by impeding YAP/TEAD nuclear translocation and reducing tumour proliferation." (PMID 41408463, 2026).
kidney cancer (2 papers, 2017 to 2023). Primary or metastatic malignant neoplasm involving the kidney. "The only cancer that lacked a methylation-driven pattern for AGTR1 was kidney cancer, although the expression change of AGTR1 in kidney cancer was identified as -3.8 and was probably influenced by tissue-specific alterations." (PMID 28178311, 2017).
nephrotic syndrome (2 papers, 2023 to 2024). A collection of symptoms that include severe edema, proteinuria, and hypoalbuminemia; it is indicative of renal dysfunction. "The role of angiotensin II in the proximal tubular uptake of sodium via angiotensin II receptor type 1 (AT1) in nephrotic syndrome is controversial." (PMID 38540182, 2024).
Peptic ulcer (2 papers, 2013 to 2025). The term peptic ulcer refers to acid peptic injury of the digestive tract, resulting in mucosal break reaching the submucosa. "The Angiotensin II receptor type 1 (AT1R) c.−521CC genotype was linked to peptic ulcers in non-ACE inhibitor/ARB users." (PMID 40399663, 2025).
postmenopausal osteoporosis (2 papers, 2017 to 2022). Metabolic disorder associated with fractures of the femoral neck, vertebrae, and distal forearm. "ACE and AGTR1 were shown to be highly expressed in the femoral head in an ovariectomized rat model of postmenopausal osteoporosis." (PMID 35445013, 2022).
retinopathy of prematurity (2 papers, 2015 to 2025). A bilateral retinopathy characterized by neovascularization, scarring, retinal detachment, and eventually blindness. "Retinopathy of prematurity (ROP) is a major cause of childhood blindness worldwide, linked to gene variants in the renin–angiotensin–aldosterone system, including angiotensin-converting enzyme (ACE) and angiotensin II receptor type 1 (AGTR1)." (PMID 39186201, 2025). "Growing evidence links RAAS genes, including ACE and AGTR1, to retinopathy of prematurity (ROP)." (PMID 39186201, 2025).
sudden cardiac arrest (2 papers, 2011 to 2012). Unexpected rapid natural death due to cardiovascular collapse within one hour of initial symptoms. "We also assessed 4 recently published gene associations for sudden cardiac arrest, validating NOS1AP (p = 4.50 × 10-2, OR = 1.15, 95% CI:1.003, 1.326), CSMD2 (p = 6.6 × 10-3, OR = 2.27, 95% CI:1.681, 2.859), and AGTR1 (p = 3.00 × 10-3, OR = 1.13, 95% CI:1.042, 1.215)." (PMID 21658281, 2011).
vesicoureteral reflux (2 papers, 2017 to 2019). Abnormal flow of urine from the urinary bladder back into the ureters. "The aim of this study was to establish the relationship of selected polymorphisms: 14094 polymorphism of the ACE, polymorphism rs1800469 of TGFβ-1, rs5443 gene polymorphism of the GNB3 and receptor gene polymorphism rs5186 type 1 AGTR1 with the occurrence of the primary vesicoureteral reflux." (PMID 27988909, 2017).
angiomyolipoma (1 paper, 2022). A neoplasm with perivascular epithelioid cell differentiation often associated with tuberous sclerosis. "In vitro evidence suggested that stimulation of AGTR1 by angiotensin II drives VEGF-A secretion in mTORC1-activated, TSC2-deficient angiomyolipoma cells, leading to increased cell proliferation, which was shown to be blocked by valsartan, an AGTR1 inhibitor." (PMID 36220392, 2022).
arteriosclerosis (1 paper, 2021). A vascular disorder characterized by thickening and hardening of the walls of the arteries. "The subjects are observational studies on the relationship between AGTR1 A1166C polymorphism and arteriosclerosis (including case-control study, cross-sectional study, and cohort study)." (PMID 33530239, 2021).
bladder urothelial carcinoma (1 paper, 2026). "Public database analysis revealed that the expression of AGTR1 and its downstream kinases, extracellular signal-regulated kinase (ERK) 1 and ERK2, was associated with overall survival in bladder urothelial carcinoma." (PMID 41549123, 2026).
cellulitis (1 paper, 2013). Inflammation of the dermis and subcutaneous tissues caused by a bacterial infection. "A subsequent denser genome scan with the HMA250K array supported the 3q22 locus, in which several SNPs in the promoter of AGTR1 (Angiotensin II receptor type I) suggestively associated with erysipelas/cellulitis susceptibility." (PMID 23437094, 2013).
cervical squamous cell carcinoma (1 paper, 2019). A squamous cell carcinoma arising from the cervical epithelium. "Three genes (MME, PGR, and AGTR1) showed >7% alteration frequency in the TCGA cervical squamous cell carcinoma." (PMID 31879572, 2019). "In the case of cervical squamous cell carcinoma, alteration frequency was greatest in MME (10%), followed by PGR (9%) and AGTR1 (8%)." (PMID 31879572, 2019).
dry eyes (1 paper, 2022). "In PCS/ME/CFS patients, the secretomotor symptoms (dry eyes, dry mouth) correlated negatively with levels of AABs against AGTR1, EDNRA, ADRA1A, ADRB1/2, and CHRM3 (black bars)." (PMID 36238301, 2022). "Similarly, the negative correlation of the secretomotor symptoms (dry eyes, dry mouth) with levels of AAB against vasoregulatory receptors AGTR1, EDNRA, ADRA1A, ADRB1/2, and CHRM3 indicate a vascular mechanism." (PMID 36238301, 2022).
E. coli infection (1 paper, 2024). "Protein network analysis indicated that genes such as FOS, CTLA4, APOA1, CEL, FRK, and AGTR1 had the strongest association with other genes, highlighting their crucial roles in E. coli infection." (PMID 39707535, 2024).
erysipelas (1 paper, 2013). An infection of the upper layers of the skin caused by species of streptococcus. "We chose two AGTR1 promoter area SNPs (rs9862062 and rs718424) that showed association to erysipelas in Haploview analysis, and genotyped them in the family material and in the acute erysipelas cohort by direct sequencing." (PMID 23437094, 2013).
Fanconi anemia (1 paper, 2021). Fanconi anemia (FA) is a hereditary DNA repair disorder characterized by progressive pancytopenia with bone marrow failure, variable congenital malformations and predisposition to develop hematological or solid tumors. "AGTR1 had positive correlations to pan-F-TBRS, EMT1-3, and angiogenesis, whereas it had negative associations with DNA damage repair, KEGG-discovered histones, Fanconi anemia, cell cycle, DNA replication, nucleotide excision repair, homologous recombination, and mismatch repair." (PMID 35083278, 2021).
Gaucher disease (1 paper, 2021). Gaucher disease (GD) is a lysosomal storage disorder encompassing three main forms (types 1, 2 and 3), a fetal form and a variant with cardiac involvement (Gaucher disease - ophthalmoplegia - cardiovascular calcification or Gaucher-like disease). "The AGTR1 Inhibitor olmesartan is neuroprotective in a chemically induced Gaucher disease model." (PMID 34550070, 2021).
gestational diabetes mellitus (1 paper, 2016). "Multiple logistic regression analysis adjusting for maternal age, fetal sex, and gestational diabetes mellitus showed significant associations between angiotensinogen (AGT) rs3789678 T/C and GH (p = 0.0088) and between angiotensin II receptor type 1 (AGTR1) rs275645 G/A and PE (p = 0.0082)." (PMID 27910864, 2016).
hydronephrosis (1 paper, 2012). Collection of urine in the renal pelvis that results in dilatation of the renal pelvis and calyces. "Mutations in the genes encoding for angiotensinogen (AGT), renin, ACE, or angiotensin II receptor type 1 (AGTR1) in mice result in severe medullary hypoplasia and hydronephrosis, a phenotype not observed in humans with AGT, renin, ACE, or AGTR1 mutations." (PMID 22685656, 2012).
Hyperbilirubinemia (1 paper, 2022). An increased amount of bilirubin in the blood. "In this study, we evaluated the effect of mild unconjugated hyperbilirubinemia induced by UGT1A1 antisense on mRNA expression of angiotensin II receptor type-1 (AT1-R) to assess the reno-toxic effects of CsA." (PMID 36295901, 2022).
hypothyroidism (1 paper, 2025). Abnormally low levels of thyroid hormone. "Fetal hypothyroidism was found to have temporal and tissue‐specific effects on the expression of many RAS genes including AGT, ACE, ACE2, AGTR1, and AGTR2." (PMID 40939099, 2025).
leiomyoma (1 paper, 2019). A well-circumscribed benign smooth muscle neoplasm characterized by the presence of spindle cells with cigar-shaped nuclei, interlacing fascicles, and a whorled pattern. "These experimental in vitro findings highlight the potential role of Ang II, through AGTR1 in the proliferation of leiomyoma cells." (PMID 31554351, 2019).
lung squamous cell carcinoma (1 paper, 2019). "AGTR1 hypermethylation is a promising biomarker in lung squamous cell carcinoma detection and diagnosis." (PMID 31781593, 2019).
multiple myeloma (1 paper, 2019). "In this study, we examine the bone marrow AGTR1 expression in multiple myeloma (MM) and its relationship with the regulation of angiogenesis and prognostic factors." (PMID 31042345, 2019).
ovarian serous cystadenocarcinoma (1 paper, 2019). A malignant serous cystic epithelial neoplasm arising from the ovary. "MME, SOX17, AGTR1, PGR, and ESR1 had the highest amplifications frequency ranging from 4% to 11% in ovarian serous cystadenocarcinoma." (PMID 31879572, 2019).
ovarian tumors (1 paper, 2017). "Studies have shown that there is a positive correlation between BRCA1 and AGTR1 levels in ovarian tumors." (PMID 28439256, 2017). "Recently, a study demonstrated, by immunohistohemical staining, that ovarian tumors express AGTR1." (PMID 28439256, 2017).
pancreatic adenocarcinoma (1 paper, 2021). "Similarly, ACE, ACE2, and AGTR1 were significant prognostic factors for overall survival (OS) in KIRC and LGG, whereas ACE, AGT, and AGTR1 were significant prognostic factors for OS in pancreatic adenocarcinoma (PAAD)." (PMID 34671200, 2021).
pheochromocytoma (1 paper, 2012). "These receptors belong to the G protein-coupled receptor family, and the presence of AGTR1 and AGTR2 in the plasma membrane of rat pheochromocytoma cells, rat kidney and many others has been well documented." (PMID 23781300, 2012).
rectal cancer (1 paper, 2021). A primary or metastatic malignant neoplasm that affects the rectum. "AGTR1 knockdown ameliorated stromal cell senescence and suppressed senescent stromal cell-triggered rectal cancer progression." (PMID 35083278, 2021). "Through Spearman correlation analysis, the association of BRCA1, CLU, AGTR1, and KL expression with the CNA value was estimated across rectal cancer." (PMID 35083278, 2021). "This study also evaluated the correlation of BRCA1, CLU, AGTR1, and KL expression with methylation levels in rectal cancer." (PMID 35083278, 2021). "For observing the effect of AGTR1 on senescent stromal cell–triggered rectal cancer progression, SW837 and SW1483 rectal cancer cells were cocultured with the conditioned medium of senescent HUVECs with AGTR1 knockdown." (PMID 35083278, 2021). "Through the cBioPortal tool, we evaluated CNAs of BRCA1, CLU, AGTR1, and KL across rectal cancer." (PMID 35083278, 2021).
Serous ovarian carcinoma (1 paper, 2019). "Serous ovarian carcinoma showed very strong expression of AGTR1 (29/30 samples were positive)." (PMID 30845964, 2019).
small artery occlusion (1 paper, 2024). "A recent study showed that the AGTR1 rs275653 AA genotype reduced the risk of small artery occlusion strokes, although it did not affect AT1R expression." (PMID 39591456, 2024). "A recent study showed that the AGTR1 rs275653 AA genotype reduced the risk of small artery occlusion strokes, although it did not affect AT1R expression levels." (PMID 39591456, 2024).
tumor (185 papers, 2004 to 2026). "Another member of the RAS pathway, the angiotensin II receptor type 1 (AGTR1) was also associated with metastatic PCa cells, while the angiotensin II receptor type 2 inhibits tumor growth, induces apoptosis, and reduces Ki‐67 and AR expression." (PMID 36329628, 2023). "We found that AGTR1 was associated with multiple genes and pathways related to tumor immune infiltration in GC." (PMID 36983741, 2023). "The presence of AGTR1, the ARBs receptor, is associated with a poor prognosis of iCCA and is highly expressed in tumour tissues and cancer‐associated fibroblasts (CAFs)." (PMID 36855786, 2023). "Overexpression of AGTR1 is typically associated with more aggressive tumor features and worse outcomes." (PMID 36505810, 2022). "AGTR1 (angiotensin II receptor type 1) is associated with tumor growth, tumor metastasis and drug resistance." (PMID 33644115, 2021). "Analysis by tumor grade showed that a significantly poorer prognosis was associated with high expression of AGTR1 when compared to lower tumor grade patients." (PMID 30845964, 2019). "Wild-type BRCA1 patients show higher tumor expression levels of AGTR1 compared to patients with BRCA1 mutations." (PMID 28439256, 2017). "Extending these observations to additional tumor types, a reduction in capillary density was observed in AGTR1 deficient mice engrafted with melanoma cells." (PMID 29240722, 2017). "Furthermore, a SNP (A1166C) in the AGTR1 has been associated with higher tumour node metastases (TNM) stage of the BCa as compared to the individuals harbouring A1166A." (PMID 25981295, 2015). "In vivo, AGTR1 facilitated early tumor engraftment and promoted tumor progression, accompanied by reduced E-cadherin and elevated N-cadherin expression, with most of these changes suppressed by LOS treatment." (PMID 41549123, 2026). "In patients with primary non-muscle-invasive bladder cancer, intravesical recurrence following transurethral tumor resection correlated with AGTR1 expression levels." (PMID 41549123, 2026). "Studies demonstrate that AGTR1 promotes tumor cell migration and invasion, facilitating metastasis by influencing extracellular matrix remodeling and cell-cell interactions." (PMID 41006647, 2025). "Ang II is also present in neutrophils, and when it binds with AGTR1, it can enhance the activity of neutrophils, thus eliminating tumor cells." (PMID 39450258, 2024). "A box plot was plotted based on sample information acquired from TCGA to represent the differential expression of AGTR1 between normal and LUAD samples, showing that AGTR1 was significantly downregulated in the tumor group." (PMID 39450258, 2024). "Through univariate Cox regression analysis, nine genes, including 3 oncogenes (HTR3C, CRHR2 and AGTR1), 6 tumor suppressor genes (CD8A, CD3E, SERPIND1, CXCR6, BMX and CD247) were proved to be correlated with the overall survival of EC patients." (PMID 38355782, 2024). "The tumour volume of T1+AGTR1+CAFs/RBE+AGTR1+CAFs showed the most significant decrease after treatment with ARBs." (PMID 36855786, 2023). "The results of Western blotting and qRT‐PCR confirmed that the expression level of AGTR1 was generally higher in CAFs than in tumour cells." (PMID 36855786, 2023). "Although the TME polarizes TAN to N2, angiotensin-converting enzyme inhibitors (ACEi) and angiotensin II type 1 receptor (AGTR1) antagonists can polarize it toward N1 to attenuate tumor growth." (PMID 37415162, 2023). "The Ang II/AGTR1(Ang II receptor) axis is suggested to have autocrine and paracrine synergistic effects on tumour progression and cancer fibrogenesis." (PMID 36855786, 2023). "Through quantitative experiments, we found that AGTR1, the target receptor of ARBs, was expressed in both iCCA‐CAFs and tumour cells." (PMID 36855786, 2023). "The ARBs strongly attenuated the viability of AGTR1+CAFs in vitro and retarded tumour progression and fibrosis in xenograft models of co‐cultured CAFs and iCCA cells." (PMID 36855786, 2023).